TMED8 (transmembrane p24 trafficking protein family member 8)
Synonyms: FAM15B
Tractability: Antibody: the Human Protein Atlas places it where antibodies can reach. PROTAC: ubiquitination databases record sites on it; its protein half-life has been measured.
Gene: Protein-coding gene on chromosome 14 (77,335,029 to 77,377,097, reverse strand). Ensembl gene ENSG00000100580.
Subcellular location (Human Protein Atlas): Plasma membrane; Vesicles
Gene Ontology:
Molecular function: protein binding; protein-macromolecule adaptor activity
Biological process: vesicle-mediated transport
Genetic constraint (gnomAD): Loss-of-function variants: 10 observed, 27.92 expected, observed/expected ratio (o/e) 0.36, 90% interval 0.22 to 0.61. The upper end of that interval is the gene's LOEUF score, 0.61, which puts it in group 2 of 6, group 1 being the genes least tolerant of losing a copy. Missense variants: 340 observed, 385.83 expected, observed/expected ratio (o/e) 0.88, 90% interval 0.81 to 0.96. Synonymous variants: 134 observed, 144.97 expected, observed/expected ratio (o/e) 0.92, 90% interval 0.8 to 1.07.
Homologues: Orthologues: macaque TMED8 (98% identical), chimpanzee TMED8 (94% identical), rabbit TMED8 (90% identical), guinea pig TMED8 (89% identical), rat Tmed8 (88% identical), dog TMED8 (86% identical), mouse Tmed8 (86% identical), pig TMED8 (86% identical), tropical clawed frog tmed8 (46% identical), zebrafish tmed8 (37% identical), Caenorhabditis elegans Y41E3.7 (31% identical), Drosophila melanogaster CG14232 (29% identical). Paralogues in human: ACBD3 (35% identical).
Diseases named in the same sentence as TMED8 in open-access papers:
TMED8 is named in the same sentence as 1 disease in open-access papers, as found by Europe PMC text mining. Sharing a sentence is not in itself a finding about the gene and the disease. The quoted sentences say what the papers report.
neuroblastoma (1 paper, 2022). Neuroblastoma (NB) is the most common solid, extracranial childhood tumor. "TMED3 played a role in promoting the progression and development of lung squamous cell carcinoma, liver cancer, and breast progression, and TMED8 methylation was a novel predictive and prognostic feature for patients with high-risk neuroblastoma." (PMID 35754792, 2022). "Recent studies proposed the idea of TMED8 as a methylated gene regulating energy metabolism in neuroblastoma, which meant TMED8 could be used as a new target for therapy, drug development, and prediction of survival." (PMID 35754792, 2022).